CALU (calumenin)
Description:
Involved in regulation of vitamin K-dependent carboxylation of multiple N-terminal glutamate residues. Seems to inhibit gamma-carboxylase GGCX. Binds 7 calcium ions with a low affinity (By similarity).
Tractability: Antibody: UniProt places it where antibodies can reach, with high confidence; its Gene Ontology location is reachable by antibodies, with high confidence; UniProt predicts a signal peptide or a membrane-spanning region. PROTAC: ubiquitination databases record sites on it; its protein half-life has been measured.
Gene: Protein-coding gene on chromosome 7 (128,739,292 to 128,773,400, forward strand). Ensembl gene ENSG00000128595.
Subcellular location: Endoplasmic reticulum membrane; Golgi apparatus; Secreted; Melanosome; Sarcoplasmic reticulum lumen
Subcellular location (Human Protein Atlas): Endoplasmic reticulum
Pathways (Reactome):
Metabolism of proteins: Post-translational protein phosphorylation; Regulation of Insulin-like Growth Factor (IGF) transport and uptake by Insulin-like Growth Factor Binding Proteins (IGFBPs)
Hemostasis: Platelet degranulation
Gene Ontology:
Molecular function: calcium ion binding; protein binding
Cellular component: endoplasmic reticulum; endoplasmic reticulum membrane; extracellular region; Golgi apparatus; melanosome; membrane; endoplasmic reticulum lumen; sarcoplasmic reticulum lumen
Genetic constraint (gnomAD): Loss-of-function variants: 9 observed, 28.24 expected, observed/expected ratio (o/e) 0.32, 90% interval 0.19 to 0.56. The upper end of that interval is the gene's LOEUF score, 0.56, which puts it in group 2 of 6, group 1 being the genes least tolerant of losing a copy. Missense variants: 217 observed, 316.08 expected, observed/expected ratio (o/e) 0.69, 90% interval 0.61 to 0.77. Synonymous variants: 88 observed, 111.74 expected, observed/expected ratio (o/e) 0.79, 90% interval 0.66 to 0.94.
Homologues: Orthologues: chimpanzee CALU (100% identical), dog CALU (99% identical), pig CALU (99% identical), guinea pig CALU (99% identical), mouse Calu (98% identical), rat Calu (97% identical), macaque CALU (93% identical), rabbit CALU (87% identical), tropical clawed frog calu (83% identical), zebrafish calua (78% identical), zebrafish calub (77% identical), Drosophila melanogaster scf (51% identical), and 1 more. Paralogues in human: RCN1 (61% identical), RCN3 (52% identical), RCN2 (37% identical), SDF4 (29% identical).
Diseases named in the same sentence as CALU in open-access papers:
CALU is named in the same sentence as 55 diseases in open-access papers, as found by Europe PMC text mining. Sharing a sentence is not in itself a finding about the gene and the disease. The quoted sentences say what the papers report.
lung carcinoma (7 papers, 2018 to 2025). "Overexpression of CALU has been associated with poor prognosis in lung cancer, colorectal cancer, and breast cancer." (PMID 41595468, 2025). "On the other hand, analysis of DEGs in validation sets indicated that the abnormal level of CALU associated with the OS of cancer patients with lung cancer (P < 0.01)." (PMID 32469983, 2020). "Through database mining, microarray analysis, proteomics, transcriptomics, and other approaches, several studies have unveiled the elevated expression of CALU in lung cancer, colon cancer, glioma, and breast cancer, positioning it as a promising biomarker." (PMID 38970088, 2024). "Moreover, we developed a signature gene panel consisted of CALU and other differentially expressed genes (DEGs) between healthy and cancer datasets retrieved from the Cancer Genome Atlas (TCGA), and estimated the diagnostic and prognostic performances of this panel in colon and lung cancer patients." (PMID 32469983, 2020). "The Kaplan–Meier survival analysis was performed to plot the OS of colon and lung cancer patients with abnormal levels of CALU, AURKA, and MCM2, in separate form and as a panel." (PMID 32469983, 2020). "Analysis of human lung cancer patients indicated a higher level of CALU and Oxysterol binding protein-like 5 (OSBPL5) in metastatic cancer cells than non-metastatic samples." (PMID 32469983, 2020). "We quantified calumenin expression in A549 lung cancer cells and IMR-90 or MRC-5 lung fibroblasts by RT-qPCR." (PMID 29892003, 2018). "Knockdown of calumenin suppressed invasiveness of lung cancer cells." (PMID 37723418, 2023). "Therefore, OSBPL5 and CALU play a role in lymph node metastasis by enhancing the invasiveness of lung cancer cells." (PMID 33504115, 2021). "Since increased cytosol calcium is able to promote cell proliferation via calcium-nuclear factor of active T cells (NFAT), we speculate that calumenin may modulate SERCA2 to promote proliferation in lung cancer cells." (PMID 29892003, 2018).
melanoma (7 papers, 2009 to 2025). A malignant, usually aggressive tumor composed of atypical, neoplastic melanocytes. "CALU has the potential to serve as an effective target for inhibiting melanoma growth, invasion, migration, and metastasis." (PMID 34688260, 2021). "This is particularly important as, except for CALU, the remaining seven EMT genes found to be up-regulated in ABCB5-enriched CTC fractions have been previously associated with melanoma metastasis, invasion, and/or tumour growth." (PMID 30769764, 2019). "CALU expression was found to be increased in mucosal melanoma tissues through microarray hybridization and gene expression analyses and immunohistochemistry." (PMID 31118065, 2019). "CALU protein from mucosa, mucosal nevi and mucosal melanoma patients was stained by immunohistochemistry." (PMID 31118065, 2019). "When comparing monocytes to melanoma cells, proteins such as VIM, LMNA, CALU, LGALS3, CTTN, and CORO1A are strongly and confidently differentially expressed." (PMID 40775377, 2025). "Mechanistically, miR-let-7b and miR-let-7c directly targeted metadherin (MTDH) and calumenin (CALU) and suppressed phospho-ERK in mucosal melanoma cells." (PMID 31118065, 2019). "Of the identified antigens, galectin-3 and HSP60 most often induce antibody responses in melanoma patients followed by calumenin and enolase I. For HSP60 and calumenin seroreactivity was also detected in healthy donors tested." (PMID 19381273, 2009). "CALU protein staining was strongly positive in mucosal melanoma, weakly positive in mucosal nevi and negative in mucosal tissue." (PMID 31118065, 2019). "Similarly, the up-regulated genes in the ABCB5 CTC fractions were involved in metastasis (CALU, CYB5R1, DUSP3, CREG1, ENDOD1), tumour growth, and/or melanoma biology (H1F0, SCNA, WIPI1, TXN2)." (PMID 30769764, 2019).
breast carcinoma (5 papers, 2016 to 2025). "In a recent proteomic study concerning the effect of the anti-tumoural natural drug gambogic acid on breast carcinoma cells, levels of calumenin were consistently decreased." (PMID 27936075, 2016).
colon carcinoma (3 papers, 2018 to 2023). "In Skrzypczak’s dataset, CALU was found highly expressed in colorectal carcinoma (fold change = 2.106) and in colon carcinoma (fold change = 2.604) versus normal samples." (PMID 37723418, 2023). "Calumenin shows an increased expression in clinical tissue samples of colon tumors and acts as a novel putative biomarker of CRC." (PMID 37723418, 2023). "Recently, calumenin was identified as a secreted protein expressed in CAFs in colon cancer, and high stromal expression of calumenin was correlated with lymph node involvement and poor survival." (PMID 29892003, 2018). "CALU was suggested to be a stromal biomarker with prognostic significance in colon cancer." (PMID 34150647, 2021).
glioma (3 papers, 2021 to 2024). A benign or malignant brain and spinal cord tumor that arises from glial cells (astrocytes, oligodendrocytes, ependymal cells). "Increased expression of calumenin was associated with poorer outcome in gliomas." (PMID 34063287, 2021). "We explored CALU expression at transcriptional level via a cohort of 998 glioma samples and demonstrated that CALU expression was positively correlated with WHO grade." (PMID 33623713, 2021). "Assuming that CALU played a vital role in regulating glioma EMT, we investigated the association between CALU and EMT markers, including N-cadherin, E-cadherin, snail, slug, and vimentin." (PMID 33623713, 2021). "Here, we analyzed clinical and transcriptome data of 998 patients, aiming at exploring the role of CALU in gliomas." (PMID 33623713, 2021). "CALU was revealed to be highly associated with TGFβ, PI3K/AKT, as well as hypoxia pathway, indicating that CALU might regulate glioma EMT through these signaling pathways." (PMID 33623713, 2021). "Furthermore, CALU seemed to be mainly involved in EMT process of glioma, potentially through modulating TGFβ, PI3K/AKT, and hypoxia pathway." (PMID 33623713, 2021). "However, the expression patterns and biological functions of CALU in gliomas have rarely been described." (PMID 33623713, 2021). "So far, very little is known about the biological function of CALU in glioma." (PMID 33623713, 2021). "Thus, unveiling the regulative mechanism of CALU may facilitate to develop a novel gene for potential glioma diagnosis and treatment." (PMID 33623713, 2021). "Moreover, CALU seemed to serve as a pro-EMT molecular target and could contribute to predict prognosis independently in glioma." (PMID 33623713, 2021). "Despite no report with regard to the pro-EMT effect of CALU, the other two members (Cab45 and EFHD2) from the same protein family have been described in EMT regulation, which indirectly supported the potential role of CALU in glioma EMT." (PMID 33623713, 2021). "Besides, CALU expression in IDH mutant glioma seemed to be universally lower than that in IDH wildtype, across different WHO grade, except for lower grade glioma (LGG) in CGGA, which exhibited apparent trends although not significant." (PMID 33623713, 2021).
lung adenocarcinoma (3 papers, 2018 to 2024). A carcinoma that arises from the lung and is characterized by the presence of malignant glandular epithelial cells. "The mRNA and protein levels of calumenin in lung adenocarcinoma are highly expressed and they are related to an unfavorable prognosis in this disease." (PMID 38970088, 2024). "As already shown, the expression level of CALU was significantly upregulated in both colon adenocarcinoma and lung adenocarcinoma samples in comparison to the normal groups (P < 0.001)." (PMID 32469983, 2020). "In this study, the proliferation of A549 lung adenocarcinoma cells was induced by CM from miR-21-expressing fibroblasts and suppressed by CM from calumenin knockdown fibroblasts." (PMID 29892003, 2018). "Here, we studied the impact of calumenin on lung adenocarcinoma and explored possible mechanisms." (PMID 38970088, 2024). "Notably, we observed an opposite expression pattern of CALU in squamous cell carcinoma compared to adenocarcinoma, such as in lung squamous cell carcinoma and lung adenocarcinoma." (PMID 38970088, 2024). "Furthermore, the expression of calumenin in lung adenocarcinoma tissue samples was examined by immunohistochemistry." (PMID 29892003, 2018). "However, the regulatory mechanism of calumenin in lung adenocarcinoma remains elusive." (PMID 38970088, 2024). "Thus, miR-21-expressing CAF-derived calumenin might function as an effector molecule in lung adenocarcinoma." (PMID 29892003, 2018).
bladder cancer (2 papers, 2023 to 2024). "Additionally, CALU has been implicated in bladder cancer prognosis, where it is involved in tumor microenvironment remodeling, gene mutations, and iron-dependent cell death." (PMID 38970088, 2024).
colon adenocarcinoma (2 papers, 2020 to 2023). "In The Cancer Genome Atlas data, higher expression of CALU was found in colon mucinous adenocarcinoma (fold change = 3.107), in cecum adenocarcinoma (fold change = 2.583), in rectal adenocarcinoma (fold change = 2.948), and in colon adenocarcinoma (fold change = 2.601) compared to normal samples." (PMID 37723418, 2023).
keloid (2 papers, 2013 to 2022). An irregularly shaped, elevated mark on the skin caused by deposits of excessive amounts of collagen during wound healing. "Of these, CALU and RCN3 showed abnormally high expression levels with lower p values in keloids; while RCN1 was uniquely present in keloids." (PMID 35435317, 2022). "We identified 206 proteins that showed significant differences in expression between keloid scars and normal skin tissues, including RCN3, RCN1, CALU, and PDGFRL which may play an import role in keloid formation." (PMID 35435317, 2022). "In our study, we found CALU, RCN3, and RCN1, the members of CREC protein family which carries out a number of functional activities, including calcium homeostasis and secretory cargo sorting, were significantly upregulated in keloids." (PMID 35435317, 2022).
lung squamous cell carcinoma (2 papers, 2019 to 2024). "In lung squamous cell carcinoma, the CALU transcript was found to be downregulated compared to normal lung tissue." (PMID 38970088, 2024). "The expression of CALU differed from cancer types and was downregulated in head and neck squamous cell carcinoma and lung squamous cell carcinoma, among others." (PMID 31118065, 2019).
lymph node metastasis (2 papers, 2021 to 2024). "Meanwhile, the TCGA database indicated a connection between high CALU expression and lymph node metastasis in LUAD, where higher CALU expression levels were associated with increased metastatic involvement." (PMID 38970088, 2024). "In summary, these comprehensive results highlight the involvement of CALU expression in cancer, particularly its upregulation of mRNA and protein in LUAD, and its association with poor prognosis, staging, and lymph node metastasis." (PMID 38970088, 2024).
astrocytoma (1 paper, 2015). "Additionally, the gene CALU was also observed to be up-regulated in GBM but not in low-grade astrocytoma or oligodendroglioma." (PMID 25866482, 2015).
COVID-19 (1 paper, 2024). A disease caused by infection with severe acute respiratory syndrome coronavirus 2. "We found three new-onset autoantibodies associated with increased severity of neuropsychiatric symptoms post-COVID-19: anti-CALU, MYO16, and SNURF IgG." (PMID 39414823, 2024).
cystic fibrosis (1 paper, 2014). Autosomal recessive disorder caused by pathogenic variants in the CFTR gene (cystic fibrosis transmembrane conductance regulator), which encodes a chloride and bicarbonate channel expressed in epithelial cells, and follow the diagnosis criteria. "Currently, it is not clear how calumenin-CFTR interaction might contribute towards the observed pathophysiology of cystic fibrosis." (PMID 25120007, 2014).
filariasis (1 paper, 2018). "A Ca2+ binding protein, calumenin, was identified as a novel and nematode-specific drug target for filariasis, due to its involvement in fertility and cuticle development in nematodes." (PMID 30428563, 2018).
head and neck cancer (1 paper, 2024). A primary or metastatic malignant neoplasm affecting the head and neck. "However, studies demonstrated lower expression of CALU in certain tumors, such as downregulation of the metastasis-related protein calmodulin precursor in head and neck cancer cell lines and hepatocellular carcinoma cells." (PMID 38970088, 2024).
heart failure (1 paper, 2021). Inability of the heart to pump blood at an adequate rate to meet tissue metabolic requirements. "In this study, we analyzed the immune infiltration profiles of CM and NF samples, and identified CALU and PALLD as potential diagnostic biomarkers for heart failure due to ischemic cardiomyopathy by using integrated bioinformatics analyses." (PMID 34926621, 2021). "To get the robust gene signature in heart failure, we overlapped genes from LASSO and SVM-RFE and got six gene signatures, including PALLD, DDX39A, CD164, CLDND1, SLC38A2, and CALU." (PMID 34926621, 2021). "We found that the expression trends of CALU and PALLD in GSE116250 were consistent with those in GSE5406, and that CALU and PALLD also had high accuracy in classifying heart failure samples, as evidenced by AUC >0.7." (PMID 34926621, 2021).
joint disease (1 paper, 2023). "Although none have been described in joints or OA, CD81, calumenin, and TMED7 are promising candidates for further studies, focusing in particular on their potential ability to influence inflammation and degradation processes, to better understand their role in joint disease." (PMID 37443777, 2023).
kidney cancer (1 paper, 2021). Primary or metastatic malignant neoplasm involving the kidney. "The association of CALU with GPX4, HSPA5 and SLC7A11 in the pan-cancer data revealed a significant relationship between CALU and ferroptosis among various tumors, especially the breast, prostate and kidney cancers where ferroptosis was more commonly observed." (PMID 34150647, 2021).
malignant glioma (1 paper, 2021). A grade III or grade IV glioma arising from the central nervous system. "CALU expression was significantly upregulated in more malignant gliomas, including higher grade, IDH wildtype, mesenchymal, and classical subtype." (PMID 33623713, 2021). "In conclusion, CALU was upregulated in more malignant gliomas and predicted much worse prognosis." (PMID 33623713, 2021).
metastatic cancer (1 paper, 2021). A carcinoma which has spread from the original site of growth to another anatomic site. "Simultaneously, CALU was demonstrated to express significantly higher levels in the metastatic cancer tissues." (PMID 33747932, 2021).
mucosal melanoma (1 paper, 2019). A melanoma that arises from a mucosal site. "In our study, it was observed that CALU, most likely CALU-15, promoted malignant progression of mucosal melanoma." (PMID 31118065, 2019). "In conclusion, our results suggested that miR-let-7b and miR-let-7c inhibited the recurrence of mucosal melanoma through inhibiting cell growth, migration and invasion, inducing cell apoptosis and cell cycle arrest by targeting MTDH and CALU." (PMID 31118065, 2019). "Our results suggested that miR-let-7b and miR-let-7c inhibited the recurrence of mucosal melanoma through inhibiting cell growth, migration, invasion and metastasis, inducing cell apoptosis and cell cycle arrest by targeting MTDH and CALU." (PMID 31118065, 2019).
osteosarcoma (1 paper, 2021). A usually aggressive malignant bone-forming mesenchymal neoplasm, predominantly affecting adolescents and young adults. "In the case of module 3 genes associated with osteosarcoma, eight are found in COSMIC (LUM, COL6A3, TNC, CALU, COL16A1, OMD, ITGB5, and DPSYL3), and two (CDH11 and OMD) are oncogenes found in OncoKB." (PMID 34570764, 2021).
pulmonary fibrosis (1 paper, 2021). Chronic progressive interstitial lung disorder characterized by the replacement of the lung tissue by connective tissue, leading to progressive dyspnea, respiratory failure, or right heart failure. "Calumenin associated with extensive cutaneous fibrosis, frequency of Raynaud phenomenon, and low complement level, and had a tendency to be higher in Ssc patients with pulmonary fibrosis." (PMID 34063287, 2021). "Interestingly, patients with pulmonary fibrosis had a tendency for higher circulatory calumenin levels (30.22 ng/mL (34.62) versus 21.5 ng/mL (12.70) p = 0.087, Mann Whitney U test)." (PMID 34063287, 2021). "There was also a tendency for higher calumenin levels in patients with pulmonary fibrosis." (PMID 34063287, 2021).
river blindness (1 paper, 2018). "Thus, selective calumenin-targeting drugs might be effective to both lymphatic filariasis and river blindness (onchocerciasis)." (PMID 30428563, 2018).